TCOF1 (treacle ribosome biogenesis factor 1)
Diseases named in the same sentence as TCOF1 in open-access papers (continued):
Sharing a sentence is not in itself a finding about the gene and the disease.
infection (8 papers, 2011 to 2025). The state of being infected such as from the introduction of a foreign agent such as serum, vaccine, antigenic substance or organism. "Among the ribosomal proteins, Treacle ribosome biogenesis factor 1(TCOF1), nuclear transport factor 2 like export factor 2(NXT2), ribosomal protein L37(RPL37), ribosomal protein L29 (RPL29) and mitochondrial ribosomal protein S18A(MRPS18A) are all up-regulated in the early stages of infection." (PMID 34092256, 2021).
TCOF1 also shares sentences with these, for which no sentence is quoted: Diamond-Blackfan anemia (4 papers); mandibulofacial dysostosis (3); dyskeratosis congenita (2); Shwachman-Diamond syndrome (2); albinism (1); Alport syndrome (1); Alstrom syndrome (1); amyotrophic lateral sclerosis (1); anemia (1); ankylosis (1); Bardet-Biedl syndrome (1); biotinidase deficiency (1); Bowen-Conradi syndrome (1); branchiootic syndrome 1 (1); cartilage-hair hypoplasia (1); Charcot-Marie-Tooth disease type 1B (1); choanal atresia (1); Clouston syndrome (1); colon cancer (1); dentinogenesis imperfecta (1); developmental delay (1); diabetes (1); erythrokeratodermia variabilis (1); familial amyloid polyneuropathy (1); fungal infection (1); gastric cancer (1); genetic disorder (1); hepatoblastoma (1); hepatocellular carcinoma (1); Hyperglycemia (1).
A further 24 diseases each share a sentence with TCOF1 in 1 paper.